IL6 (interleukin 6)
Diseases named in the same sentence as IL6 in open-access papers (continued):
Sharing a sentence is not in itself a finding about the gene and the disease.
respiratory infections (48 papers, 2013 to 2026). "HCoV-OC43, a common human coronavirus, typically causes mild respiratory infections but can induce cytokine and chemokine responses in infected individuals, such as IL6, TNF-α, IL-8, CCL2 (MCP-1), and CCL5." (PMID 40872743, 2025). "Beyond MP, the IL-6/STAT3 pathway has been implicated in a variety of other pediatric respiratory infections." (PMID 41137299, 2025). "IL-6, a crucial cytokine, has a role in the immediate response to infection and is linked to the seriousness of respiratory infections and chronic illnesses." (PMID 38999876, 2024). "This mRNA virus causes an inflammatory respiratory infection that mainly affects the lower respiratory tract and is marked by a rise in proinflammatory cytokines like interleukin 6 (IL-6) and interferon-gamma (IFN-γ)." (PMID 37519527, 2023). "Interaction between IL-6 response to E. coli and infant age suggests that IL-6 response to E. coli’s associations with respiratory infections and any ID diminished with advancing infant age." (PMID 35769951, 2022). "Each doubling of the IL-6 response to S. enterica was associated with 23% lower risk for any respiratory infection; by contrast, each doubling of the IL-6 response to E. coli was associated with a 29% increase in risk for gastrointestinal infection." (PMID 35769951, 2022). "Our study identified the neutrophil-associated biomarkers MPO, NE, and IL-6 as promising indicators with different suggestive roles in respiratory infections and interstitial lung diseases in patients with ASS and DM." (PMID 36199667, 2022). "Less is known about the role of IL-6 in respiratory infections of other cause." (PMID 35622838, 2022). "Here we show that Interleukin-6, a soluble mediator commonly associated with inflammation and seen in humans with severe respiratory infection, is actually critical in promoting the resolution of the host response to respiratory virus infection and limiting disease." (PMID 28953978, 2017). "Using a respiratory infection model, we evaluated the accumulation of human neutrophils, cytokine secretion (IL-6 and IL-8), bacterial clearance, and overall survival compared to control groups." (PMID 40102849, 2025). "In the respiratory infection model, this approach resulted in enhanced accumulation of human neutrophils, increased secretion of IL-6 and IL-8, superior bacterial clearance, and reduced mortality rates compared to the control group." (PMID 40102849, 2025). "All in all, we have demonstrated that elevated IL-6 in serum is not a predictor of RP-ILD, elevated circulating NE, MPO, and IL-6 all suggest respiratory infections, and finally, AAT is an indicator of poor lung function in ASS and DM patients." (PMID 36199667, 2022). "Above results indicated a strong performance of MPO, NE, and IL-6 to identify patients with possible respiratory infections." (PMID 36199667, 2022). "Our study found that circulating NE, MPO, and IL-6 were significantly elevated in both ASS and DM patients with comorbid respiratory infections and have good diagnostic value." (PMID 36199667, 2022). "Elevated serum NE, MPO, and IL-6 levels are suggestive of respiratory infections, whereas decreased circulating IL-6 is predictive of RP-ILD." (PMID 36199667, 2022). "High concentrations of IL-6 are regularly seen after severe respiratory infection, and are often considered an indicator of un-checked disease." (PMID 28953978, 2017). "We find that IL-6 is produced rapidly upon respiratory infection, but that elevated concentrations are seen throughout infection." (PMID 28953978, 2017). "In another double blind phase II trial, SLE patients treated intravenously with Sirukumab, a fully human anti-IL6 monoclonal antibody, suffered from some minor respiratory infections." (PMID 27050763, 2016).
respiratory infections (continued). "The impact of these studies could be manifold, including the potential to evaluate the role of IFN-λ or IL-6 as prognostic biological markers in aged individuals with respiratory infections and the possibility of modulating these targets." (PMID 41301463, 2025). "IL-6 might serve as a decision support to assess the severity of pulmonary involvement in patients with respiratory infections." (PMID 37733154, 2023). "Inflammation may play a role in cardiovascular events after respiratory infection, and elevated IL-6 and IL-10 cytokine concentrations at hospital discharge have been associated with early cardiovascular mortality." (PMID 33602977, 2021). "Relevant for the current review are previous observations suggesting a reduced risk for respiratory infections with the MeD and especially a reduced risk of inflammation, with a decrease in C-reactive protein (CRP) and pro-inflammatory cytokines, such as interleukin (IL)-6 and IL-1β." (PMID 37048015, 2023). "Seropositive individuals had higher levels of CRP, TNF, and IL-6 in circulation 1–3 months post-symptom onset; but in samples from individuals 6–9 months post-symptom onset, levels were equivalent to those individuals who were seronegative and were recovered from other respiratory infections." (PMID 34835045, 2021). "Future prospective multicenter cohorts should enroll diverse COPD patients with acute lower respiratory infections across severity strata, employing standardized CRP assays alongside inflammatory mediators (IL-6, TNF-α)." (PMID 40630494, 2025). "In another study of patients with IIM, it was found that the serum levels of IL-6, NE and MPO-DNA complexes were higher in subjects with respiratory infections and ILD (Reviewed in 47)." (PMID 36923415, 2023). "In particular, we have found that circulating IL-6 was decreased in patients with RP-ILD and significantly increased in respiratory infections." (PMID 36199667, 2022). "In the acute phase, leptin is co-produced together with the main inflammatory interleukins (IL), IL-6, IL-1, and tumor necrosis factor-α (TNF-α), and acts on the sense of hunger and on the immune response, especially in respiratory infections." (PMID 32630032, 2020). "These genes are directly involved in innate immune sensing (TLR, MYD88, JAK/STAT), and inflammation (IL-6, IFN, TNF, IL-10, IL-22) which are two common host signaling pathways activated by bacteria and viruses during acute respiratory infections." (PMID 27532264, 2016). "However, at 7 dpi, monocytes/macrophages in the other animal (NV19) showed enrichment in pathways typically upregulated during a respiratory infection, such as TNF-⍺ and IL-6 signaling, and inflammatory response, complement, and coagulation." (PMID 39066335, 2024). "Although respiratory infections are an important predisposing factor for RP-ILD, the results of this study tell us very clearly that elevated IL-6 suggested infection rather than RP-ILD, and that the combined NE and MPO assays provide better clarity." (PMID 36199667, 2022). "Respiratory infection with the attenuated Live Vaccine Strain (LVS) and the highly virulent SchuS4 strain of Ft engenders intense peribronchiolar and perivascular inflammation, but fails to elicit select pro-inflammatory mediators (e.g., TNF, IL-1β, IL-6, IL-12, and IFN-γ) within the first ∼72 h." (PMID 23554897, 2013). "Heightened IL-6 measurements seen in patients hospitalized with severe respiratory infection are likely to reflect increased inflammation, but not indicate elevated IL-6 production at the earliest stages of infection, where our data indicates it might play a protective role." (PMID 28953978, 2017). "Elevated circulating IL-6 level does not imply the development of RP-ILD, but more likely represents respiratory infection, so it is inappropriate to apply IL-6 levels as an indication to initiate tocilizumab." (PMID 36199667, 2022).
respiratory infections (continued). "MPO (P = 0.049), NE (P = 0.049), and IL-6 (P = 0.014) were significantly higher in ASS and DM patients with respiratory infections compared to patients without respiratory infections." (PMID 36199667, 2022).
bacterial meningitis (47 papers, 2007 to 2025). Inflammation of the membranes surrounding the brain and spinal cord due to a bacterial infection. "Furthermore, a meta-analysis about the diagnostic performance of interleukin-6 and interleukin-8 for bacterial meningitis reported a sensitivity of 91% and specificity of 93% for IL-6 as well as a sensitivity of 95% and specificity of 89% for IL-8." (PMID 38678151, 2024). "In another prospective study, all patients with proven bacterial meningitis had CSF IL-6 more than 500 pg/mL." (PMID 35330399, 2022). "The ΔrpoE strain stimulated HBMECs to release more IL-6 and IL-8 than the WT strain did, which are crucial inflammatory mediators that elicit leukocyte infiltration in bacterial meningitis." (PMID 35630325, 2022). "In another study, the level of IL-6 in the CSF of patients with a diagnosis of purulent bacterial meningitis with a more severe course reached 392 ± 199 pg/mL." (PMID 35330399, 2022). "Detailed Bayesian statistics was performed on three cytokines with key roles in inflammation in bacterial meningitis: IL-6, IL-8 and TNFα." (PMID 34620928, 2021). "IL-6 is considered an early response proinflammatory mediator that is upregulated during bacterial meningitis." (PMID 33318141, 2021). "A variety of cytokines have been demonstrated in the CSF of patients with bacterial meningitis, including interleukin-6 (IL6), interleukin-8 (IL8), interleukin-1-beta (IL1b), and tumor necrosis factor alpha (TNFa)." (PMID 34680826, 2021). "The expression of IL-6 and IL-10 in the serum of patients with enterovirus/bacterial meningitis is abnormal, while the expression of IL-6 and IL-10 in patients with bacterial meningitis is higher than that of viral meningitis." (PMID 34925324, 2021). "Multiple studies have demonstrated elevated levels of TNF-α, IL-6, and IL-8 in the CSF of patients with bacterial meningitis, especially in the pediatric population." (PMID 30626412, 2019). "Elevated IL-8, IL-1β, TNF-α, and IL-6 have routinely been shown to be elevated in bacterial meningitis." (PMID 30626412, 2019). "They found that TNF-α, IL-1, IL-6, IL-8, IL-10, and IL-12 levels were significantly elevated in infants with bacterial meningitis." (PMID 30626412, 2019). "Interleukin-6 (IL-6) concentration in the CSF is often used as a biomarker of neuroinflammation in bacterial meningitis and progressive neuro-Behçet’s disease." (PMID 29454354, 2018). "Cytokines such as TNF- α and IL-6 play an important role in bacterial meningitis to initiate and orchestrate the innate immune response in the early phase of the disease." (PMID 28915816, 2017). "High levels of IL-6 were also reported in bacterial meningitis of children and experimental listeriosis, suggesting this cytokine plays a relevant role." (PMID 27965668, 2016). "IL6 level in admission of 1.8 patients with bacterial meningitis was less than 100pg and in 7.19 of patients with viral meningitis was greater than 100pg." (PMID 23483792, 2012). "Measurement of CSF and serum IL6 is potentially useful for differentiating normal CSF patients from bacterial meningitis." (PMID 23483792, 2012). "IL-6 concentration in the CSF and serum were significantly raised in cases of bacterial meningitis (P = 0.001, P = 0.01) but HS-CRP concentration in the CSF and serum were not significantly raised in cases of bacterial meningitis (P = 0.46, P = 0.29)." (PMID 23483792, 2012). "The meningococcal isolates from 254 patients from a prospective nationwide observational cohort study of 696 adults with community-acquired bacterial meningitis in the Netherlands (period, 1998–2002) were analyzed for their ability to induce IL-6." (PMID 19390612, 2009). "Of note, the association between the third ventricle ratio and IL6 course in CSF was present, independent of the occurrence of bacterial meningitis during SAH." (PMID 37048667, 2023).
bacterial meningitis (continued). "Additionally, it has been implicated in the generation of IL-6 and TNF-α pro-inflammatory cytokines through the stimulation of NFκB toward other forms of bacterial meningitis caused by N. meningitidis and B. bergdorferi." (PMID 35401413, 2022). "Moreover, it was shown that IL-6 played an important role in increasing brain permeability in a model of bacterial meningitis." (PMID 23785528, 2013). "Mean serum IL6 in bacterial meningitis was (50.01) and in viral (10.64)." (PMID 23483792, 2012). "CSF IL6 concentration is significantly higher in bacterial meningitis than in aseptic meningitis." (PMID 23483792, 2012). "Mean IL6 of CSF in bacterial meningitis was (180.74) and in viral (39.08)." (PMID 23483792, 2012). "However, in the subgroup of patients with a CSF leucocyte count 5-1,000/mm3, other biomarkers such as a combination of CRP and IL6 demonstrated better predictive accuracy in differentiating bacterial meningitis from other diseases and bacterial vs viral CNS infections." (PMID 40471671, 2025). "Comparison of mean IL6 CSF concentration in these two groups of children by use of Mann - Whitney test, show that, difference is significant (P < 0.001); and mean IL6 CSF in children with bacterial meningitis is significant higher than in patient with normal CSF." (PMID 23483792, 2012). "This is exemplified by a systematic review summarising the literature specifically for paediatric bacterial meningitis which reported pooled meta-analyses accuracy metrics for the best studied biomarkers, CRP, procalcitonin, IL6, IL8, TNF-alpha and ferritin." (PMID 40471671, 2025). "The significantly higher CSF concentrations of IL-6, TNF-α, and MCP-1 are usually found in the acute phase of patients with bacterial meningitis, especially in patients with a fatal outcome." (PMID 37111486, 2023). "The ELISA quantification results (pg/mg protein) showed that intranasal administration of bacterial meningitis in rats significantly stimulated the pro-inflammatory cytokines production, TNF-α, IL-6 and IL-1β, compared with the controls." (PMID 36015052, 2022). "A2M along with IL-6 and C-Reactive-Protein (CRP) levels in the CSF can indicate blood-cerebrospinal fluid barrier (BCB) damage in bacterial meningitis as part of the acute phase reaction." (PMID 35401413, 2022). "In the pathogenesis of cerebral injury in bacterial meningitis, TNF-α, IL-6, and IL-1β are major early response cytokines that trigger, often in synergy, a cascade of inflammatory mediators, including other cytokines, oxygen intermediates, and chemokines." (PMID 34437417, 2021). "The most sensitive ones described in the literature are cytokines such as IL-6, IL-10, TNF-alfa and INF-gamma, which are increased in the CSF of children with bacterial meningitis." (PMID 31063510, 2019). "In bacterial meningitis, multiple cytokines including CXCL10 (IP10), CCL2, CCL7 (MCP-3), CCL4 (MIP-1β), CCL5, CXCL12, IL6, IL8, and IL17 have been shown to be increased in the acute phase of the disease (; Pinto)." (PMID 31727097, 2019). "Cytokines such as IL-6 and TNF-α play an important role in bacterial meningitis and are synthesized in large quantities by monocytes, macrophages, and leukocytes in response to bacterial stimuli." (PMID 27057100, 2016). "We selected IL-1 beta, IL-6 and TNF alpha for the quantitative reverse transcriptase PCR, since they are known to be the major inflammatory cytokines detected in the CSF during bacterial meningitis, as control the house keeping genes GAPDH and HPRT1 were used." (PMID 23874613, 2013). "Cytokines and chemokines, including IL-8, IL-6, TNFα, MCP-1 and IL-1β, have been found in CSF during bacterial meningitis." (PMID 23448224, 2013). "In contrast to IL-6, LOTUS may reflect disease activity of wider range of CNS diseases such as viral and bacterial meningitis, CNS sarcoidosis, and MS." (PMID 29454354, 2018).
bacterial meningitis (continued). "Plasma concentrations of MCP-1, sCD14, IL-6, and IL-10 were significantly higher in patients with community-acquired pneumonia (CAP; n = 10) and infective endocarditis (IE; n = 11) compared to those with bacterial meningitis (BM; n = 18)." (PMID 29769838, 2018). "Additionally, pyroptosis causes the excessive production of cytokines and chemokines including TNF-α, IL-1β, IL-6, CCL3, CXCL-1, CXCL-2, etc. in bacterial meningitis which can also result in inflammatory mediator-induced neuronal damage." (PMID 26683708, 2015). "Increased levels of IL-6 and TNF were detected in the CSF of patients with bacterial meningitis." (PMID 23483792, 2012). "Moreover, prospective studies are warranted to compare IL-6 levels in newborns who subsequently develop bacterial meningitis with those who do not, to evaluate its predictive potential for central nervous system involvement." (PMID 41302151, 2025). "Still, we could not distinguish enteroviral meningitis from bacterial meningitis with the parameters of CSF cytokines IL‐2, IL‐6, IL‐10, TNF, and IFN‐γ." (PMID 31912935, 2020). "In this study, we measured two inflammatory mediators, IL6 and HS-CRP, in CSF and serum of children who were admitted to pediatric emergency room and finally the level of these two mediators in three groups of patients were compared: Bacterial meningitis, viral meningitis, and normal CSF patients." (PMID 23483792, 2012). "Thus, we could not distinguish enteroviral meningitis from bacterial meningitis with the parameters of CSF cytokines IL‐2, IL‐6, IL‐10, TNF, and IFN‐γ." (PMID 31912935, 2020).